ALB (albumin)
Diseases named in the same sentence as ALB in open-access papers (continued):
Sharing a sentence is not in itself a finding about the gene and the disease.
glomerulonephritis (56 papers, 2010 to 2026). A renal disorder characterized by damage in the glomeruli. "The detection of certain proteins, albumin in particular, in the urine serves as the marker of renal pathology called glomerulonephritis (GN), which is caused by the inflammation of glomeruli." (PMID 32660060, 2020). "In addition, we observed that having glomerulonephritis and lower albumin is associated with a lower antibody response." (PMID 38140206, 2023). "Multivariable logistic regression analysis revealed that an eGFR< 30 ml.min− 1 (1.73 m2)− 1 at renal biopsy was associated with ANCA associated glomerulonephritis in renal-biopsied RA patients (OR 25.13 [1.07–592.06], p = 0.046) adjusted for age, sex, serum albumin and hemoglobin." (PMID 35459111, 2022). "Albumin reduction in cases of glomerulonephritis due to AAV involvement should be considered an indirect marker of inflammation and protein loss from persistent proteinuria." (PMID 39459426, 2024). "We assessed the level of AT1R antibodies in 136 patients with different types of glomerulonephritis and systemic vasculitis and we observed kidney function and proteinuria, serum albumin and total protein levels for 2 years." (PMID 36152104, 2022). "Cpd-7 was administered orally once or twice daily at 100 mg kg−1 for four weeks to female NZB/W F1 mice with a urinary albumin/creatinine ratio over 300 mg g−1, which marked the onset of glomerulonephritis." (PMID 33060576, 2020). "As with albumin, immunoglobulins are also passed in the urine in patients with glomerulonephritis, with the accompanying decrease in serum concentration." (PMID 32079183, 2020). "Much to our surprise, upon analysis of all organs, these mice displayed necrotic livers and a kidney phenotype with severe accumulation of albumin and structural distortion reminiscent of glomerulonephritis." (PMID 27213588, 2016). "Compared to normal controls, there was a 1000-fold increase in the urine albumin excretion at day 1 of glomerulonephritis, which increased 3-fold further at day 7 of disease and then remained stable between days 7 and 14 of disease." (PMID 26700873, 2015). "Serum albumin has the potential to reflect the time-averaged proteinuria, which is known to account for the prognostic effects of proteinuria over time in studies of glomerulonephritis." (PMID 39421234, 2024). "Interestingly, we also found that patients with ANCA glomerulonephritis had higher levels of baseline albumin and lower initial doses of prednisone than patients with LN." (PMID 32406300, 2020). "Moreover, they differed in age, gender, albumin and glomerulonephritis as primary renal disease." (PMID 33076736, 2020). "Hypertensive patients with glomerulonephritis had lower eGFR than normotensive patients (p < 0.001) and more prominent damage in glomerular and tubulointerstitial compartments, in addition to higher excretion of albumin/creatinine, IgG/creatinine, and α1-microglobulin/creatinine (p < 0.001 for all)." (PMID 32492793, 2020). "n = number; GFR = glomerular filtration rate; ACR = albumin creatinine ratio; PKD = polycystic kidney disease; GN = glomerulonephritis; DM = diabetes." (PMID 23803596, 2013). "RA patients with ANCA associated glomerulonephritis, as opposed to those with primary glomerulonephritis, tended to have lower eGFR and hemoglobin and higher levels of serum albumin at biopsy." (PMID 35459111, 2022). "Albumin level in the mesangial proliferative (non-IgA) glomerulonephritis do not differ significantly from the other groups." (PMID 36152104, 2022). "In this regard, Kritz and coworkers have suggested that albumin uptake by tubular cells is not an absolute prerequisite for tubulo-intertitial injury in mice with glomerulonephritis." (PMID 20976140, 2010). "The distribution of gender, BMI, serum lipid levels, BUN, creatinine levels, eGFR, albumin concentration, hemoglobin levels, CKD stage, or concurrent glomerulonephritis were not significantly different in the two cohorts." (PMID 40282868, 2025).
glomerulonephritis (continued). "Albumin level in c-ANCA vasculitis group was higher than this level in the membranous nephropathy, focal and segmental glomerulosclerosis, lupus nephritis and mesangial proliferative (non-IgA) glomerulonephritis groups." (PMID 36152104, 2022). "Albumin level in p-ANCA vasculitis group was higher compared to membranous nephropathy, focal and segmental glomerulosclerosis and mesangial proliferative (non-IgA) glomerulonephritis groups." (PMID 36152104, 2022).
tuberculosis (56 papers, 2008 to 2026). A chronic, recurrent infection caused by the bacterium Mycobacterium tuberculosis. "Multivariate analysis in proven tuberculosis (n = 264) indicated MLR associated with low serum albumin, high white cell counts and a positive culture; values were higher in sputum smear-positive pulmonary tuberculosis (S+PTB)." (PMID 34460817, 2021). "This increase in rifampicin CL/F in malnourished tuberculosis patients is directly linked with poor drug absorption along with low serum albumin concentrations and induction of hepatic enzymes after administration of multiple doses of rifampicin." (PMID 31694244, 2019). "Patients in the nursing- and healthcare-associated tuberculosis group had markedly lower levels of serum albumin and hemoglobin, and higher levels of C-reactive protein." (PMID 30423855, 2018). "One study in India identified serum albumin concentrations <3.2 g/dL as a risk factor for increased mortality in HIV-infected patients with tuberculosis." (PMID 27899066, 2016). "At baseline,the tuberculosis group had lower serum selenium levels than did the control group.The conversion of bacteriological tests was associated with the CRP/albumin ratioand serum selenium levels 60 days after treatment initiation." (PMID 25029650, 2014). "Having low serum albumin levels has been associated with a higher risk of death in HIV-related tuberculosis and in patients initiating antiretroviral therapy." (PMID 23997952, 2013). "In tuberculosis patients, the inter-individual variation in drug response may be linked with the reported changes in plasma albumin concentration." (PMID 31694244, 2019). "Gender, age, previous tuberculosis, smoking history, lymphocyte count, albumin count, dose of GCs, the use of immunosuppressants and type of systemic vasculitis were included in a multivariable logistic regression analysis." (PMID 39838164, 2025). "In the present study, albumin levels were reduced in tuberculosis patients compared with controls (P<0.001) and after proper antituberculosis treatment, it started to rise gradually from intensive to continuous phase of treatment." (PMID 37791165, 2023). "In tuberculosis, the level of albumin decreases while globulin increases leading to a low albumin to globulin (A/G) ratio, and electrophoresis of serum proteins are good diagnostic approach and provides essential information for monitoring treatment outcomes." (PMID 37791165, 2023). "While the difference in total protein levels approached significance (p = 0.0941), there was a significant difference in albumin levels between the control subjects (3.9 g/dL ± 0.5) and the tuberculosis patients (3.3 g/dL ± 0.5) (p < 0.0011)." (PMID 38201359, 2023). "Albumin-based nanoparticles loaded with isoniazid and rifampicin represent a promising approach for the treatment of tuberculosis." (PMID 37447420, 2023). "There is a need for clinicians to search for abnormalities of serum sodium, serum potassium, serum calcium and serum albumin in tuberculosis patients in routine clinical practice." (PMID 33889232, 2021). "Tuberculosis is a chronic infection disease, and long-term chronic infection of M. tuberculosis will lead to chronic metabolic deficit and increased depletion of ALB." (PMID 34589441, 2021). "The incorporation of plasma albumin concentration changes in tuberculosis population resulted in improved predictions, as the rifampicin-tuberculosis PBPK model has successfully captured the decrease in rifampicin CL/F reported previously in the literature." (PMID 31694244, 2019). "The incorporation of pathophysiological changes in albumin concentration in the tuberculosis population revealed improved prediction of clearance." (PMID 31694244, 2019). "It has been reported that the plasma albumin concentrations are altered in tuberculosis patients and these changes can potentially affect the ADME of low hepatic clearance drugs." (PMID 31694244, 2019).
tuberculosis (continued). "The unbound fraction (fu) of rifampicin is increased in tuberculosis patients as the plasma albumin concentration declines, which in turn can increase the CL/F of rifampicin." (PMID 31694244, 2019). "Due to the presence of clear published information on the decrease in plasma albumin concentration in tuberculosis patients, these pathophysiological changes were most relevant to the ADME of administered drugs in this disease." (PMID 31694244, 2019). "Multivariable analysis revealed that systemic corticosteroid use, tuberculosis, lymphocytopenia, low serum albumin, and high serum C-reactive protein (CRP) levels were significantly associated with indeterminate QFT-GIT results." (PMID 28732078, 2017). "Among tuberculosis patients in multivariable analyses, sex, age and VDBP were associated with 25D, and age and albumin with 1,25D." (PMID 28449659, 2017). "Gender (p = 0.02), country (p < 0.001), race (p = 0.007), prior tuberculosis (TB) (p < 0.001), hemoglobin (p = 0.008), albumin (p < 0.0001) and log10 CRP (p = 0.006) were significant risk factors for baseline serum selenium deficiency." (PMID 25401501, 2014). "Baseline levels of serum albumin, total protein and bilirubin in rats before treatment with anti-tuberculosis drugs." (PMID 18601745, 2008). "We grouped patients according to the mean PNI value of 45 and found that the low PNI group had significantly lower serum total protein and albumin concentrations and higher NRS scores, confirming that PNI can also be used to assess nutritional risk in tuberculosis patients." (PMID 36506012, 2022). "tuberculosis with or without anti-tuberculous medications was associated with significant reduction in serum albumin, serum sodium and serum calcium in this study." (PMID 33889232, 2021). "The changes in albumin concentrations occurring in tuberculosis may affect ADME of low hepatic clearance drugs like rifampicin." (PMID 31694244, 2019). "Therefore, the change in albumin concentration was the only pathophysiological modification that was incorporated into the developed tuberculosis model." (PMID 31694244, 2019). "Further studies are needed to assess whether albumin or total cholesterol is a better indicator of trace element concentrations in the serum in patients with tuberculosis." (PMID 26197334, 2015). "In the multivariate analysis, being previously treated for tuberculosis (adjusted HR [aHR] 3.23, 95% CI 1.68 to 6.24), low albumin concentrations (aHR 0.74 per increase of 1 g/dL, 95% CI 0.58 to 0.95), and low CD4+ lymphocyte concentrations were independently associated with increased mortality." (PMID 26347376, 2015). "The relationshipbetween CRP and albumin levels might be a useful tool for assessing the bacteriologicalconversion in patients with tuberculosis." (PMID 25029650, 2014). "The present study aims to assess the serum ceruloplasmin-to-albumin ratio in patients with pulmonary tuberculosis (PTB), investigating its potential as a diagnostic and prognostic marker in TB therapy." (PMID 39006642, 2024). "In addition, they evaluated four mycobacterial media: Middlebrook 7H11 with additives and OADC (oleic acid, albumin, dextrose, and catalase) supplement A (7H11-A), Middlebrook 7H11 with another supplement trademark (7H11-B), tuberculosis blood agar (B83), and Stonebrink’s medium." (PMID 35889961, 2022). "Our case group had lower levels of TC, ALB, and MCV, likely due to the high replication rate and activity of tuberculosis in active pulmonary tuberculosis patients, which leads to greater nutritional consumption." (PMID 39582970, 2024). "Laboratory tests should involve a total and differential white cell count, culture, total protein and albumin, serum-ascites albumin gradient (SAAG), cytology analysis, tuberculosis testing, lactate dehydrogenase (LDH), triglyceride, bilirubin, hemoglobin, amylase, and others if needed." (PMID 39982238, 2025).
tuberculosis (continued). "Additionally, the study seeks to compare the serum ceruloplasmin-to-albumin ratio in patients with PTB before and after undergoing anti-tuberculosis treatment (ATT)." (PMID 39006642, 2024). "PCR for JCV and tuberculosis DNA was negative However 13 children had mildly elevated albumin levels (0.66–1.65 g%0)." (PMID 37082207, 2023). "For instance, BMI and total cholesterol were significantly lower in patients with tuberculosis compared with control patients, while the serum albumin levels of the two groups were not significantly different." (PMID 26197334, 2015). "Our study is unique and the first to report changes in acute phase reactants (albumin, CRP, and beta-2-microglobulin) as measures of inflammation and how their levels relate to repletion of body composition components during treatment of tuberculosis." (PMID 22567264, 2011). "Further studies on larger populations are required whether albumin and globulin could be predictors of stronger measures of success of treatment like non-relapse diseases and insignificant death related to tuberculosis." (PMID 37791165, 2023).
melanoma (55 papers, 1995 to 2025). A malignant, usually aggressive tumor composed of atypical, neoplastic melanocytes. "A cross-sectional study of 644 patients with malignant melanoma showed that albumin-corrected calcium levels were positively associated with the stage of the disease." (PMID 39764412, 2024). "Low albumin has been described as associated with poor OS across multiple cancers however the studies of this factor in melanoma are sparse." (PMID 36290885, 2022). "Taking advantage of the systemic T cell responses induced by albumin/AlbiVax, we then investigated immunotherapy of metastatic melanoma, a primary death cause of melanoma patients." (PMID 29203865, 2017). "EM revealed a marked loss of pigmentation in the melanoma MALME-3M cells treated with albumin-associated lipids, in accordance with the downregulation of MLANA gene expression." (PMID 23961369, 2012). "These superior antitumor effects of albumin-encapsulated liposomes against melanoma may be associated with a higher uptake via energy- and clathrin-dependent endocytosis pathways compared to albumin nanoparticles." (PMID 33810483, 2021). "In conclusion, this study confirms the importance of the dynamic changes in hematological indicators such as NLR, PLR, and ALB in predicting the efficacy of PD-1 immunotherapy in patients with advanced malignant melanoma." (PMID 41561757, 2025). "Dynamic monitoring of peripheral blood NLR, PLR, and ALB provides critical insights for predicting PD-1 immunotherapy efficacy in patients with advanced malignant melanoma." (PMID 41561757, 2025). "This study found that the dynamic changes in hematological indicators such as NLR, PLR, and ALB have significant prognostic value in patients with advanced malignant melanoma undergoing PD-1 immunotherapy." (PMID 41561757, 2025). "While prior investigations have explored immunonutritional markers—including albumin—in melanoma patients undergoing immunotherapy, these studies have primarily centered on baseline measurements or single-timepoint assessments." (PMID 41561757, 2025). "Our machine learning model identified serum albumin levels as the most significant predictor of treatment response and prognosis in melanoma patients receiving IFN-α1b therapy." (PMID 39600700, 2024). "Chemotherapy has been the main treatment of advanced malignant melanoma, including dacarbazine, temozolomide, albumin‐bound paclitaxel, and so forth." (PMID 38279601, 2024). "Albumin nano shells improve contrast, cancer cytotoxicity, and collateral damage to healthy primary cells in a melanoma spheroid model." (PMID 37375846, 2023). "In multivariable analysis, baseline characteristics associated with OS across melanoma, NSCLC, and RCC included serum albumin concentration, age, region, eosinophil count, MLR, and ALC." (PMID 37962239, 2023). "Nanocomposites of rare-earth NPs encased in human serum albumin (ReANC) have been used to monitor tumour growth and spread in melanoma animal models." (PMID 37375846, 2023). "In this regard, Chen and team came up with hyaluronan (HA, 49 kDa) attached cationic bovine serum albumin (BSA) NPs loaded with PTX for CD44 targeted melanoma therapy." (PMID 36635761, 2023). "The only predictors of progression-free survival on univariable and multivariable analysis were albumin and melanoma." (PMID 38144534, 2023). "PNI is a nutritional indicator that positively correlates with albumin levels and is viewed as a novel independent prognostic factor for predicting OS in patients with malignant melanoma." (PMID 35495765, 2022). "Albumin-encapsulated liposomes accumulated at a higher level in melanoma and pancreatic ductal adenocarcinoma compared to albumin nanoparticles." (PMID 33810483, 2021). "It was shown that thiolated albumin (obtained by the incubation of albumin and sodium polysulfide) significantly inhibited melanin synthesis in B16 melanoma cells." (PMID 33050223, 2020).